DPEP1 (dipeptidase 1)
Diseases named in the same sentence as DPEP1 in open-access papers (continued):
Sharing a sentence is not in itself a finding about the gene and the disease.
tumor (continued). "Quantification of staining intensity by Image J software demonstrated that 39% of the area in tumor stage I samples, 44% in tumor stage II, 55% in tumor stage III, and 61% in tumor stage IV were DPEP1 positive, whereas 12% in normal tissues was DPEP1 positive." (PMID 26824987, 2016). "We further demonstrated that overexpression of DPEP1 suppressed tumor cells invasiveness and increased sensitivity to chemotherapeutic agent Gemcitabine." (PMID 22363658, 2012). "Further evaluation in an independent validation cohort (N = 27) confirmed that DPEP1 (dipeptidase 1) expression was decreased (T: N ratio ∼0.1, P<0.01) in tumors as compared with non-tumor tissues." (PMID 22363658, 2012). "Overall, a deeper understanding of the make-up of these tumors could lead to the identification of signaling pathways important for DPEP1-dependent tumor formation that allows for a distinctly different tumor milieu in terms of immune composition." (PMID 40178918, 2025). "Thus, DPEP1 offers a promising target for drugs like cilastatin, which inhibit vascular sprouts without crossing the blood-brain barrier, potentially reducing tumor metabolic support." (PMID 40319462, 2025). "We furthered this finding by inducing tumor formation in DPEP1-KO mice to show a reduction in cells with markers for neutrophil activation and an influx of CD8+ T cells, highlighting DPEP1’s causal role in immune exclusion rather than just being a gene that is part of an IEX signature." (PMID 40178918, 2025). "Thus, the role of DPEP1 in tumor progression is controversial and the molecular mechanism by which it regulates tumor progression and aggressiveness remains poorly understood." (PMID 26824987, 2016). "Future studies that involve assessing the T cell phenotypes in these DPEP1-KO mice as well as tumor responsiveness to ICI could lead to the development of combination treatments for reversing an immune exclusion phenotype, as we found an upregulation of PD-L1 in the KO setting." (PMID 40178918, 2025). "In addition, functional assays revealed that DPEP1 silencing could significantly suppress the HB cell proliferative, colony formation, migration, and invasion capacity in vitro, and knockdown of DPEP1 in vivo resulted in decreased HB tumor growth." (PMID 31541079, 2019). "The G2M score also was enriched in DPEP1-KO Ad/ACA cells in comparison with the WT counterpart, in agreement with the larger tumor size in DPEP1-KO mice." (PMID 40178918, 2025). "A number of studies have reported a role for DPEP1 in CRC, showing its upregulation in tumor tissue and the connections between its well-established enzymatic activity and tumorigenesis." (PMID 40178918, 2025). "RT‐qPCR analysis demonstrated that, of nine TRmRNAs, DPEP1, FGF1 and MPP7 were largely expressed in normal tissues, whereas the other six mRNAs exhibited elevated expression levels in tumour tissues." (PMID 40673609, 2025). "By intersecting these genes, we identified three genes (PLA2G2A, DPEP1, and G0S2) that were upregulated in primary and recurrent tumor tissue." (PMID 40519301, 2025). "DPEP1 and ASCL2 formed a positive feedback loop regulation mode, which increased the tolerance of tumor cells to chemotherapeutic drugs." (PMID 35670012, 2023). "In this way, DPEP1 and ASCL2 formed a positive feedback loop regulation mode, which increased the tolerance of tumor cells to chemotherapeutic drugs." (PMID 35670012, 2023). "Among these six hub genes, DEPTOR, DPEP1, NAT8, and SUSD2 were expressed at their highest levels in normal tissues, whereas PLOD2 and SLC7A5 were expressed at their highest levels in tumor thrombi." (PMID 37328520, 2023). "We have previously shown that DPEP1 is part of a 4-gene immune exclusion (IEX) signature in MSS CRC that correlates with worse progression-free survival and CD8+ T cell exclusion from the tumor proper." (PMID 40178918, 2025). "Mice lacking DPEP1 during carcinogen-induced tumorigenesis have altered tumor burden, histology, and molecular features." (PMID 40178918, 2025).
tumor (continued). "Seventy percent of the DPEP1-KO mice, but none of the WT mice, had a prolapsed colon at time of sacrifice, likely reflecting the increased tumor burden." (PMID 40178918, 2025). "DSS alone did not result in increased DPEP1 expression in the colon of non–tumor-bearing mice compared to untreated controls." (PMID 40178918, 2025). "Understanding how DPEP1 interacts with immune cells in CRC and how it relates to overall tumor phenotypes such as microsatellite status might expose a therapeutic vulnerability to overcome resistance of MSS CRC to ICI." (PMID 40178918, 2025). "Although accumulating evidence suggests that DPEP1 is involved in cancers, the mechanisms by which this enzyme inhibits or promotes tumor progression and aggressiveness are not known." (PMID 26824987, 2016). "The top differentially expressed transcripts between tumor and non-tumor were TPX2, DCBLD2 and ANLN which were significantly increased in tumors (T∶N ratio>2.0, P<0.01), and CDO1, DPEP1, C7, ALDH1A1 and NR3C2 which were significantly decreased in tumors (T∶N ratio<0.2, P<0.01)." (PMID 22363658, 2012). "In contrast, DPEP1, HADH, PLIN2, SCD5, SLC44A4, and UGT8 may function to suppress tumor growth via the regulation of immune cells with antitumor activity such as resting memory CD4 T cells, resting NK cells, M2 macrophages, resting and activated DCs, and resting mast cells." (PMID 38090559, 2023). "In addition, two tumor-associated proteins FAP (fibroblast activation protein/seprase) and DPEP1 (dipeptidase 1) were absent from healthy and perilesional ECM." (PMID 26940881, 2016). "To date, DPEP1 has only been studied for its enzymatic activity in the context of CRC, whereas its newly described role in neutrophil binding and its ability to shape the tumor microenvironment (TME) have not been examined in CRC." (PMID 40178918, 2025).
cancer (19 papers, 2012 to 2025). A tumor composed of atypical neoplastic, often pleomorphic cells that invade other tissues. "Between transcripts linked to the first phase, the AHCY (encodes adenosylhomocysteinase), CYP2B7P1 (encodes cytochrome P450 2B7P1), and DPEP1 (encodes dipeptidase 1) expression increased with cancer growth in subsequent stages of the disease." (PMID 41465541, 2025). "Low DPEP1 or high TPX2 expression was associated with poor cancer-specific mortality for all patients in the combined cohort (P<0.01, Kaplan-Meier log rank)." (PMID 22363658, 2012). "Dipeptidase 1 (DPEP1) expression was analyzed using the cancer genome atlas (TCGA) and genotype‐Tissue Expression pan‐cancer data." (PMID 35670012, 2023). "Nevertheless, the molecular mechanism of cancer depends on the type and stage of cancer, and the role of DPEP1 expression in cancer is still controversial." (PMID 34490047, 2021). "To explore DPEP1 expression pattern in different cancers, we analyzed the expression levels of DPEP1 mRNA in various types of cancers using The Cancer Genome Atlas (TCGA) and Genotype-Tissue Expression (GTEX) database." (PMID 31541079, 2019). "We also found that the enhanced expression of DPEP1 increases cancer cell invasiveness, whereas its depletion by RNA interference causes the opposite effect." (PMID 26824987, 2016). "Dehydropeptidase 1 (DPEP1) is a zinc-dependent metalloproteinase that is expressed aberrantly in several cancers." (PMID 26824987, 2016). "Functional evidence that DPEP1 inhibits cancer cell invasion and enhances sensitivity to gemcitabine, suggests DPEP1 as a candidate target for designing therapeutic strategies." (PMID 22363658, 2012). "Overall, this study clarifies DPEP1’s association with Wnt-driven MSS CRC and opens the door for exploring DPEP1’s immunomodulatory roles in cancer that could be widely translatable, with the goal of making MSS tumors responsive to ICI." (PMID 40178918, 2025). "DPEP1, a protein associated with inflammation and poor cancer prognosis, has not been directly linked to MI, but its genetic variants are associated with cardiovascular disease risk markers." (PMID 39715222, 2024). "Dysregulation of DPEP-1 in a variety of cancers can have an impact on cancer progression." (PMID 39668834, 2024). "Moreover, survival analysis for DPEP1 in pan‐cancer was performed with the best cutoff value for DPEP1 mRNA expression." (PMID 35670012, 2023). "DPEP1 gene is involved in suppression of cell proliferation and cancer invasiveness." (PMID 34262595, 2021). "The results suggested that DPEP1 was highly expressed in most cancers." (PMID 31541079, 2019). "Studies have shown that DPEP1 affects the invasion of cancer cells, and because the expression of DPEP1 decreases with pathological differentiation, it can be used as a genetic marker for the treatment of cancer." (PMID 30079033, 2018). "The role of DPEP1 in different types of cancer is controversial." (PMID 28410206, 2017). "Finally, a pharmacological inhibitor of DPEP1 suppresses cancer cell invasion in vitro and liver metastasis in vivo." (PMID 26824987, 2016). "The PHKG2 and RNF40 genes are either overlapping or close to the sequences of SCAR marker BC13-4, while SCAR marker BC10-1 is in the intron and overlap the DPEP1 gene, suggesting that alterations in the expression of these genes could contribute to cancer progression." (PMID 28410206, 2017). "In contrast to DPEP1, mechanistic studies regarding CD73-positive EVs in cancer are more established, including a report that CD73 is enzymatically active in B cells, although few studies are directly related to CRC." (PMID 37840781, 2023). "Deconvolution analysis on bulk mRNA sequencing data from TCGA revealed positive endothelial cell infiltration in DPEP1-overexpressing samples and predominantly negative T cell infiltration across cancers." (PMID 40319462, 2025).
cancer (continued). "We utilized FAVS to flow sort EVs double-positive for CEA and DPEP1 from the plasma of CRC patients as a means of detecting EVs released from the cancer rather than other sources." (PMID 37840781, 2023). "When stratified by resection margin status (positive vs. negative), both DPEP1 and TPX2 were associated with cancer-specific mortality in resection margin positive patients (P<0.01, Kaplan Meier log rank)." (PMID 22363658, 2012). "Moreover, among the enriched genes in the group of cancer areas in the dHGP, we detected many genes known to enhance inflammatory reactions in cancer by promoting the NFκB pathway (IKBKB, FKBP4), activating lymphocytes (TNFSF9, HLA-F) or recruiting neutrophils (DPEP1)." (PMID 36691028, 2023).
kidney disease (6 papers, 2021 to 2025). "Genome-wide association analyses revealed DPEP1 as a kidney disease risk gene in kidney proximal tubules, and further molecular investigation on cisplatin-associated kidney injury indicated its regulative function in ferroptosis and apoptosis." (PMID 35860471, 2022). "In recent genome-wide association studies for kidney disease, Dpep1 and Chmp1a, were identified as key regulators of ferroptosis." (PMID 36090053, 2022). "At the molecular level, Dpep1 and Chmp1 were shown to alter cellular iron trafficking, ultimately favoring the development of kidney disease." (PMID 36090053, 2022). "Our analysis prioritized both DPEP1 and CHMP1A as kidney disease risk genes in kidney proximal tubules, likely mediating the effect of the eGFR GWAS signal observed on chromosome 16." (PMID 34426578, 2021). "Dpep1 and Chmp1a levels also strongly and negatively correlated in mouse models of kidney disease induced by UUO, FA, APOL1, and PGC1a." (PMID 34426578, 2021). "Here we identify two kidney disease genes Dipeptidase 1 (DPEP1) and Charged Multivesicular Body Protein 1 A (CHMP1A) via the triangulation of kidney function GWAS, human kidney expression, and methylation quantitative trait loci." (PMID 34426578, 2021). "Here we identified DPEP1 and CHMP1A as kidney disease genes via the triangulation of genome-wide association studies, human kidney mQTL and eQTL data." (PMID 34426578, 2021). "To understand the role of Dpep1 in kidney disease development, we generated mice with genetic deletion of Dpep1 using CRISPR/Cas9 technology." (PMID 34426578, 2021). "Cellular studies indicate that both Dpep1 and Chmp1a are important regulators of a single pathway, ferroptosis and lead to kidney disease development via altering cellular iron trafficking." (PMID 34426578, 2021). "Collectively, these results suggest a kidney-specific mQTL/eQTL effect of rs164748, which prioritized both DPEP1 and CHMP1A as kidney disease risk genes." (PMID 34426578, 2021). "Our studies indicate that pharmacological targeting of ferroptosis through Dpep1 or Chmp1a in kidney tubule cells could offer therapeutic benefits for patients with kidney disease." (PMID 34426578, 2021). "This highlights the potential therapeutic benefits of pharmacologically targeting ferroptosis through DPEP1 and/or CHMP1 in patients with kidney disease to prevent multiple forms of CKD." (PMID 36090053, 2022). "Here, the authors investigate a kidney disease GWAS locus with functional genomics data, CRISPR editing and mouse experiments to identify DPEP1 and CHMP1A as putative kidney disease genes via ferroptosis." (PMID 34426578, 2021). "We identify DPEP1 and CHMP1A as kidney disease genes and important regulators of ferroptosis." (PMID 34426578, 2021).
cardiovascular disease (3 papers, 2020 to 2024). "This study is the first to identify DPEP1 as a potential therapeutic target for MI, indicating its potential value in cardiovascular disease treatment." (PMID 39715222, 2024).
infection (2 papers, 2021 to 2023). The state of being infected such as from the introduction of a foreign agent such as serum, vaccine, antigenic substance or organism. "Among the signaling cluster, significantly enhanced expression of Cd200, Camp, Chia1, Ctla2a, Dpep1, Mrc1, and Serpina1b was observed in the wild-type mice on day 7 post-infection." (PMID 34690967, 2021). "However, using receiver operating characteristic curves, we identified four to 48 candidate biomarkers of infection depending on the pathogen, including seven overlapping biomarkers (DSG2, PCBP1, MGAM, APOA4, DPEP1, GOT1, and IGFALS)." (PMID 38193073, 2023). "infections; APOA4, DPEP1, and GOT1 were negative predictors while IGFALS was a positive predictor." (PMID 38193073, 2023).
kidney (1 paper, 2021). "Expression levels of acute kidney injury markers Kim1 and Lcn2, and cytokines Ccl2 and Cd68, were lower in the cisplatin-injected Dpep1+/− mice when compared to wild-type littermates." (PMID 34426578, 2021).
neurological diseases (1 paper, 2021). "Seven of these proteins have cis-acting pQTLs that colocalise with or are causal for neurological diseases: DDR1, IL12, NEP, CD33, DPEP1, GPNMB, and LEPR." (PMID 34857772, 2021).
DPEP1 also shares sentences with these, for which no sentence is quoted: -intestinal inflammation (1 paper); actinic keratosis (1); adenocarcinoma (1); alcoholism (1); arthropathies (1); astrocytoma (1); cervical cancer (1); cognitive decline (1); colon adenocarcinoma (1); colorectal adenocarcinoma (1); coronary atherosclerosis (1); cutaneous melanoma (1); dementia (1); endotoxemia (1); heart failure (1); kidney cancer (1); liver cancer (1); lung carcinoma (1); melanoma (1); membranous nephropathy (1); metabolic disease (1); metastatic disease (1); mucinous ovarian cancer (1); myeloma (1); non-melanoma skin carcinoma (1); Obesity (1); oculocutaneous albinism (1); ovarian serous cystadenocarcinoma (1); Parkinson disease (1); peripheral neuropathy (1).
A further 7 diseases each share a sentence with DPEP1 in 1 paper.